PHKG1 (phosphorylase kinase catalytic subunit gamma 1)
Description:
Catalytic subunit of the phosphorylase b kinase (PHK), which mediates the neural and hormonal regulation of glycogen breakdown (glycogenolysis) by phosphorylating and thereby activating glycogen phosphorylase. In vitro, phosphorylates PYGM, TNNI3, MAPT/TAU, GAP43 and NRGN/RC3 (By similarity).
Synonyms: PHKG
Tractability: Small molecule: a structure with a bound ligand is known; a high-quality ligand is known; it belongs to a druggable protein family. PROTAC: a small molecule that binds it is known.
Target class: CAMK protein kinase group; Kinase; Enzyme; Protein Kinase; CAMK protein kinase PHk family
Gene: Protein-coding gene on chromosome 7 (56,079,923 to 56,093,012, reverse strand). Ensembl gene ENSG00000164776.
Pathways (Reactome):
Metabolism: Glycogen breakdown (glycogenolysis)
Gene Ontology:
Molecular function: phosphorylase kinase activity; ATP binding; calmodulin binding; enzyme binding; protein kinase activity; protein serine kinase activity; protein serine/threonine kinase activity; tau-protein kinase activity
Biological process: glycogen catabolic process; carbohydrate metabolic process; glycogen metabolic process; signal transduction
Cellular component: phosphorylase kinase complex; cytoplasm; cytosol
Genetic constraint (gnomAD): Loss-of-function variants: 45 observed, 43.9 expected, observed/expected ratio (o/e) 1.02, 90% interval 0.81 to 1.31. The upper end of that interval is the gene's LOEUF score, 1.31, which puts it in group 5 of 6, group 1 being the genes least tolerant of losing a copy. Missense variants: 422 observed, 469.8 expected, observed/expected ratio (o/e) 0.9, 90% interval 0.83 to 0.97. Synonymous variants: 190 observed, 193.77 expected, observed/expected ratio (o/e) 0.98, 90% interval 0.87 to 1.11.
Homologues: Orthologues: chimpanzee PHKG1 (99% identical), macaque PHKG1 (99% identical), dog PHKG1 (95% identical), pig PHKG1 (95% identical), rabbit PHKG1 (94% identical), guinea pig PHKG1 (94% identical), rat Phkg1 (94% identical), mouse Phkg1 (93% identical), tropical clawed frog phkg1 (76% identical), zebrafish phkg1a (74% identical), zebrafish phkg1b (73% identical). Paralogues in human: PHKG2 (63% identical), CAMK2D (34% identical), CAMK2B (33% identical), CAMK2G (33% identical), CAMK2A (32% identical), DCLK1 (30% identical), DCLK2 (29% identical), CAMK1D (29% identical), CAMK1G (29% identical), CAMK1 (28% identical), DCLK3 (28% identical), PNCK (28% identical), and 10 more.
Diseases named in the same sentence as PHKG1 in open-access papers:
PHKG1 is named in the same sentence as 10 diseases in open-access papers, as found by Europe PMC text mining. Sharing a sentence is not in itself a finding about the gene and the disease. The quoted sentences say what the papers report.
Cirrhosis (1 paper, 2022). A chronic disorder of the liver in which liver tissue becomes scarred and is partially replaced by regenerative nodules and fibrotic tissue resulting in loss of liver function. "The screened GYS1, PYGL and PHKG1 genes play crucial roles in the glycogenolysis step of the glucagon signaling pathway, and their overexpression destabilizes glycogenolysis and predisposes one to glycogen storage disease, which can lead to cirrhosis and liver fibrosis." (PMID 36430769, 2022).
Kabuki syndrome (1 paper, 2016). Kabuki syndrome (KS) is a multiple congenital anomaly syndrome characterized by typical facial features, skeletal anomalies, mild to moderate intellectual disability and postnatal growth deficiency. "Our studies identified markedly reduced expression of PHKG1 in two Kabuki syndrome subjects and decreased expression of IRX5 in one subject." (PMID 27670201, 2016). "On the basis of these data, we speculate that KMT2D regulation of IRX5 and PHKG1 contributes to the pathogenesis of Kabuki syndrome." (PMID 27670201, 2016).
lung carcinoma (1 paper, 2014). "The method was applied to the A549 lung cancer cell line, and we identified specific kinases known to have an important role in this type of cancer (TGFBR2, EGFR, PHKG1 and CDK4)." (PMID 24961498, 2014).
tumor (4 papers, 2010 to 2021). "Also, the PhKG1 (the γ-subunit) of the holoenzyme phosphorylase kinase, involved in activation of glycogen phosphorylase, has been shown to be upregulated in several human tumour samples, also involved in tumour progression, angiogenesis and tumour metabolism." (PMID 26882899, 2016). "Eight genes centromeric to SEPT14 (ZNF713, MRPS17, GBAS, PSPH, CCT6A, SUMF2, PHKG1 and CHCHD2) were amplified in tumour 4 only." (PMID 21170331, 2010). "In the case of PHKG1, we found that the protein was more abundant in cells of tumour 4 than in cells of tumours without amplification of that gene." (PMID 21170331, 2010).
cancer (2 papers, 2014 to 2023). A tumor composed of atypical neoplastic, often pleomorphic cells that invade other tissues. "Among the PPI proteins, six kinases were found to be associated with cancer pathways, including mTOR complex 1 (mTORC1), Janus kinase 1 (JAK1), Activin receptor type 1C (ACVR1C), Phosphorylase kinase catalytic subunit gamma 1 (PHKG1) and mitogen-activated protein kinase 4 (MAPK4)." (PMID 37355516, 2023).
PHKG1 also shares sentences with these, for which no sentence is quoted: Alzheimer disease (1 paper); glycogen storage disease (1); liver fibrosis (1); lung adenocarcinoma (1); neurodegenerative disease (1).